APOE (apolipoprotein E)
Diseases named in the same sentence as APOE in open-access papers (continued):
Sharing a sentence is not in itself a finding about the gene and the disease.
Alzheimer disease (continued). "We analyzed dorsolateral prefrontal cortex (DLPFC) from 34 Alzheimer's disease (AD) cases and controls with different ApoE genotypes from the Emory Brain Bank by mass spectrometry-based proteomics." (PMID 30618606, 2018). "Analysis of individuals with APOE ε33 genotype included 5704 individuals for Alzheimer’s disease, all dementia and vascular dementia, 5601 for ischemic cerebrovascular disease and 5443 for ischemic heart disease." (PMID 29534716, 2018). "LDL-R also is expressed in the brain and helps in clearing apolipoprotein-E, which is responsible for the formation of amyloid-β which accumulates in the brain of Alzheimer's disease patient." (PMID 29770231, 2018). "During middle age, cognitively healthy APOE-ε4 carriers already show several brain alterations that resemble those of Alzheimer's disease (AD), but to a subtler degree." (PMID 29793545, 2018). "As a relevant example, Apolipoprotein E (APOE) isoform epsilon 4 is negatively linked to longevity for being responsible for mortality of stem cell pool, and by causing Alzheimer’s Disease (AD) and worsening CVD outcome." (PMID 30347645, 2018). "Genetic variations in apolipoprotein E (APOE) and proximal genes (PVRL2, TOMM40, and APOC1) are associated with cognitive function and dementia, particularly Alzheimer’s disease." (PMID 29739406, 2018). "The objective of this preliminary study was therefore to test if tau load and brain structure differ by APOE ε4 in Alzheimer’s disease." (PMID 30086796, 2018). "Analysis of individuals with the APOE ε33 genotype included 52,219 individuals for Alzheimer’s disease, all dementia, and vascular dementia, 50,583 for ischemic cerebrovascular disease, and 48,095 for ischemic heart disease." (PMID 29534716, 2018). "There are three major forms of Apolipoprotein E, and individuals who carry a version known as ApoE4 are up to 10 times more likely to develop Alzheimer’s disease than those who carry other variations." (PMID 30375977, 2018). "The Old PIB+ ApoE ε4+ showed relatively few differences with the Alzheimer's disease group, but exhibited moderate differences with the Other Old group." (PMID 29527500, 2018). "Apolipoprotein E (ApoE) has been shown to play an important role in lipid metabolism, progression of cardiovascular and Alzheimer’s disease, and the pathogenesis of several infectious diseases such as HIV-1." (PMID 30496280, 2018). "A notable commonality between the Old PIB+ ApoE ε4+ and the Alzheimer's disease groups is the low metabolic correlation strength in ROIs in the entorhinal cortex and medial temporal lobe compared to young and other old subjects." (PMID 29527500, 2018). "The viral concept of Alzheimer’s disease (AD) proposes that herpes simplex virus type 1 (HSV1) in brain of apolipoprotein E gene (APOE-ε4) carriers accounts for some 60% of cases." (PMID 30405395, 2018). "We recently reported that rs9472817-C/G, an intronic variant of neuronal mitochondrial uncoupling protein-4 (UCP4/SLC25A27) gene affects the risk of late onset Alzheimer's disease (LOAD), and that the variant's effect is strongly dependent on APOE-ε4 status." (PMID 30425186, 2018). "Best known is the ε4 allele of the apolipoprotein E gene (APOE), a well-established genetic risk factor for late-onset (after age 65) Alzheimer’s disease." (PMID 30339707, 2018). "The significant association between the SNP rs429358 and the latent variable scores for hippocampus reflects the importance of APOE for Alzheimer’s disease." (PMID 30390165, 2018). "Similar patterns of relative correlation strength emerged across the subgroups of older adults, although the PIB+ ApoE ε4+ subgroup appeared to be in an intermediary stage between normal aging and Alzheimer's disease." (PMID 29527500, 2018). "The presence of both apolipoprotein E (APOE) ε4 allele and amnestic mild cognitive impairment (aMCI) are considered to be risk factors for Alzheimer’s disease (AD)." (PMID 30319395, 2018).
Alzheimer disease (continued). "The APOE gene has three common alleles—E2, E3, and E4, with APOE4 being the strongest genetic risk factor for developing Alzheimer’s Disease (AD)." (PMID 30586872, 2018). "In summary, we have performed a neuroimaging genetics study for Alzheimer’s disease (AD) to explore the relationship between genetic variations in the APOE gene and brain ROIs measured by voxel based morphometry (VBM)." (PMID 28291242, 2017). "The role of different genotypes of apolipoprotein E (apoE) in the etiology of Alzheimer’s disease is widely recognized." (PMID 28218653, 2017). "This study sought to evaluate gender and APOE genotype-related differences in the concentrations of cerebrospinal fluid (CSF) biomarkers for Alzheimer’s disease (AD) and cerebrovascular injury across the life span of cognitively normal adults." (PMID 28673336, 2017). "Citrate-capped IrO2NPs were modified with anti-Apolipoprotein E antibodies (αApoE) for the detection of the ApoE alzheimer disease biomarker, with a detection limit of 68 ng mL−1." (PMID 28387718, 2017). "Of the three human apoE isoforms (E2, E3, and E4), E4 is a risk factor for age-related cognitive decline (ACD) and Alzheimer's disease (AD), particularly in women." (PMID 29100334, 2017). "Accordingly, Cx3cr1−/−mice that express increased amounts of APOE in MPs, including MCs, are protected against beta-amyloid deposition in Alzheimer disease mouse models." (PMID 29270905, 2017). "Baseline characteristics in our study were as expected for a prodromal Alzheimer's disease population, including the CSF biomarker profile; percentage of APOE ε4 carriers; and IWG-1, IWG-2, and NIA-AA criteria." (PMID 29097166, 2017). "APOE, HP, and CRYL1 have all been associated with Alzheimer’s Disease, the pathology of which involves lipid and cholesterol pathways." (PMID 28206976, 2017). "For example, apoE plays a role in many brain disorders, including Alzheimer’s disease, mild cognitive impairment, multiple sclerosis, traumatic brain injury, Creutzfeldt-Jakob disease (CJD) and some others." (PMID 28695482, 2017). "This study was designed to explore the influence of apolipoprotein E (APOE) on blood phospholipids (PL) in predicting preclinical Alzheimer's disease (AD)." (PMID 28333036, 2017). "These experiments showed that a form of apoE that protects against Alzheimer’s disease was more effective in transporting beta-amyloid proteins across the walls of blood vessels than other forms of apoE." (PMID 28994390, 2017). "We found viability effects of variants near the APOE and CHRNA3 genes, which are associated with the risk of Alzheimer disease and smoking behavior, respectively." (PMID 28873088, 2017). "Insulin metabolism as well as insulin-altering therapies in Alzheimer’s disease are modulated by APOE status, while irisin reduces diet-induced obesity and insulin resistance in vivo." (PMID 29143599, 2017). "APOE is known for its role in arteriosclerosis, Alzheimer’s disease, Parkinson’s disease and cardiovascular diseases." (PMID 28129359, 2017). "Recent evidence suggests that APOE plays a role in normal brain function and a number of cardiovascular, neurodegenerative (such as Alzheimer disease, Parkinson’s disease and multiple sclerosis) as well as metabolic (e.g. type 2 diabetes mellitus) diseases." (PMID 28688452, 2017). "Overlapping pathologies between Alzheimer's disease and PD suggest a possible role for ApoE in the etiology of PD." (PMID 29326545, 2017). "Apolipoprotein E (APOE) and sortilin-related receptor (SORL1) genes act on the same metabolic pathway and have been associated with Alzheimer’s disease (AD) characterized by hippocampal impairment." (PMID 28229235, 2017). "Mutations in APP, APOE, PSEN1, PSEN2 and MAPT genes were found to cause Alzheimer’s disease pathogenesis." (PMID 26784894, 2016).
Alzheimer disease (continued). "The genetic background of the more common late-onset Alzheimer's disease (LOAD) is more complicated, and only the variant of the apolipoprotein E (APOE) gene has been consistently related to the risk of this disease." (PMID 27750211, 2016). "A report from the Alzheimer’s Disease Neuroimaging Initiative (ADNI) database shows the influence of ApoE ɛ 4 dose on clinical and neuroimaging biomarkers across the AD spectrum (from cognitive normal to AD patients with severe cognitive impairment." (PMID 27891223, 2016). "The presence of the allele 4 of the apolipoprotein E (APOE) gene, a known genetic risk factor for Alzheimer’s disease (AD), affects the progression of neurodegenerative processes in TBI patients and is associated with increased neurologic complications." (PMID 27853449, 2016). "Her family history was positive for Alzheimer's disease in her father, and her ApoE genotype was 2/4." (PMID 27294343, 2016). "The REVEAL study, which examined the impact of genetic education, APOE-e4 testing, and a counseling program for adult children of Alzheimer’s disease patients, provides some important insights into future behavior." (PMID 27955707, 2016). "Studies have shown that clusterin, similar to its predecessor apolipoprotein E (ApoE), plays a vital role in the pathogenesis of Alzheimer's disease (AD)." (PMID 27516739, 2016). "PVRL2 is located 17 kb downstream from the apolipoprotein E (APOE) gene and has also been associated with severity of multiple sclerosis, late-onset Alzheimer’s disease, and peripheral T-cell lymphomas." (PMID 25688259, 2015). "The effect on the risk of Alzheimer disease depends on the existence of an ApoE e4 allele, which was found to intensify the biochemical disturbances that are characteristic of AD including beta amyloid deposition, tangle formation, neuronal cell death, and synaptic plasticity." (PMID 26578083, 2015). "Multi-adjusted hazard ratios and 95% CIs of dementia and Alzheimer disease related to diabetes, HHEX_23, IDE_9, and APOE in the Kungsholmen Project and SNAC-K." (PMID 26173052, 2015). "ABCA1also controls apoE lipidation, and has a role in Alzheimer's disease,including an impact on amyloid β (APP, P05067) deposition and clearance." (PMID 26650446, 2015). "One small-scale study suggested that the differences in APOE methylation between brains with late-onset Alzheimer's disease and normal brains increase with age." (PMID 25476875, 2015). "Apolipoprotein E (APOE) and oxidative damage were correlated with the risk of Alzheimer’s disease (AD)." (PMID 26404360, 2015). "An emerging finding was that older people with the ε4 allele of the gene for apolipoprotein E (APOE), a strong genetic risk factor for Alzheimer’s disease (AD), are more likely to have faster cognitive decline." (PMID 26574747, 2015). "Sex differences in neuropsychiatric symptoms of Alzheimer's disease (AD) have been demonstrated in previous studies, and apolipoprotein E (ApoE) ε4 status influences psychiatric manifestations of AD." (PMID 26538817, 2015). "The recovered ordering shows less variation in the sequence for amyloid+, APOE+ or amyloid+APOE+ individuals than for the whole population, most likely reflecting that the former are a more homogeneous group with archetypical Alzheimer’s disease pathology." (PMID 25012224, 2014). "The data also suggest that the APOE pathways interact with genetically regulated mitochondrial functions in the response to acute injury, as previously reported in Alzheimer disease." (PMID 24523223, 2014). "Abnormal functions of ApoE can lead to hypercholesteremia, and increased production of amyloid, a protein associated with both AMD (geographic atrophy) and Alzheimer’s disease." (PMID 24919117, 2014).
Alzheimer disease (continued). "The presence of at least one ε2 allele was associated with higher APOE levels and a lower risk for CHD, whereas at least one allele of the isoform ε4 was shown to predict lower APOE levels and a higher potential to develop CHD and Alzheimer disease." (PMID 25064003, 2014). "Genetic polymorphisms in the APOE ɛ and TOMM40 ‘523' poly-T repeat gene loci have been associated with significantly increased risk of Alzheimer's disease." (PMID 25247594, 2014). "The APOE ε2/3/4 genotype has been associated with low-density lipoprotein cholesterol (LDL-C) and Alzheimer disease." (PMID 25073452, 2014). "Apolipoprotein E is a major target in Alzheimer disease, because it is known to modulate the amyloid-β aggregation in the brain being involved in the neurodegeneration." (PMID 24884737, 2014). "The interaction between GP73 and APOE gives a hint to understand the role of GP73 in the pathogenesis of Alzheimer’s disease." (PMID 24608522, 2014). "This study investigated the effects of the gene Apolipoprotein E (APOE), a risk factor for Alzheimer's disease, on BOLD signals." (PMID 24959130, 2014). "For example, the ɛ4 allele of apolipoprotein E (APOE) gene is well known to increase risk of cardiovascular disease and Alzheimer's disease." (PMID 25045704, 2014). "The association of genes such as brain-derived neurotrophic factor (BDNF) and apolipoprotein-E (ApoE) with cognitive decline and late-onset Alzheimer’s disease (AD) has been investigated." (PMID 25339899, 2014). "The ordering of the CSF biomarkers in amyloid+ and APOE+ individuals supports the ordering of CSF biomarkers predicted by earlier hypothetical models of Alzheimer’s disease progression: CSF amyloid-β1–42, phosphorylated tau, total tau." (PMID 25012224, 2014). "Changes within the DMN have been observed in healthy aging, Alzheimer’s disease, individuals with amnestic mild cognitive impairment, and in APOE-ε4 carriers." (PMID 24699668, 2014). "Peripheral blood Apolipoprotein E (ApoE) levels have been proposed as biomarkers of Alzheimer’s disease (AD), but previous studies on levels of ApoE in blood remain inconsistent." (PMID 24558469, 2014). "In tissue from patients with Alzheimer’s disease, the sizes of APOE ε3,3 neurons were larger than those of APOE ε4,4 neurons (286 ± 23 μm2 vs 227 ± 25 μm2, p < 0.01)." (PMID 24252240, 2013). "Manipulation of apoE levels and lipidation within the brain has been proposed as a therapeutic target for the treatment of Alzheimer’s disease." (PMID 23601557, 2013). "One factor influencing the prevalence of both vascular and Alzheimer's disease is the apolipoprotein E (APOE) genotype." (PMID 26316992, 2013). "The link between apolipoprotein E (apoE) and Alzheimer’s disease is likely due in large part to the impact of apoE on the metabolism of amyloid β (Aβ) within the brain." (PMID 23601557, 2013). "A major genetic suspect for Alzheimer's disease is the pathological conformation assumed by apolipoprotein E4 (ApoE4) through intramolecular interaction." (PMID 24324968, 2013). "The APOE mononucleotide entropy of 1.8673 would suppress very slightly the mono-nucleotide correlation of mRNA versus CDS in Late-onset Alzheimer's disease studied sequences from R2 of 0.9948 (N = 5) to 0.9944 (N = 6)." (PMID 23662159, 2013). "Thus, aberrant cholinergic transmission induced by arsenic could play a part in reduced adult neurogenesis seen in our studies, along with upregulation of the genes Apbb1 and ApoE, both of which are associated with Alzheimer’s disease and have been shown to impair adult neurogenesis." (PMID 24019935, 2013). "The Apolipoprotein E (APOE) 4 polymorphism influences aging and age-related diseases including the risk for Alzheimer's disease." (PMID 23509683, 2013). "Our cross-sectional study showed that the interaction between apolipoprotein E4 (ApoE4) and angiotensin converting enzyme (ACE) inhibitors was associated with Alzheimer’s disease (AD)." (PMID 23948883, 2013).
Alzheimer disease (continued). "Five hundred twenty patients with Creutzfeldt-Jakob disease (CJD, n = 350), Alzheimer's disease (n = 71) and cerebral small vessel disease (n = 99) were assessed for their ApoE genotype." (PMID 24386372, 2013). "Prior brain imaging studies that evaluated the influence of genes on the effects of age on brain glucose metabolism focused on the apolipoprotein E (APOE-ε4) allele, which is a major susceptibility gene for late onset Alzheimer’s disease." (PMID 23717434, 2013). "Other variables, as reflected in a family history of Alzheimer's disease, influence hippocampal cortical thickness independently and through interaction with the APOE genotype." (PMID 24228185, 2013). "The APOE sequence has the lowest entropy among the studied sequences, and all CDSs have lower entropy than mRNAs in the Late-onset Alzheimer's disease studied sequences." (PMID 23662159, 2013). "We studied these parameters in different apoE models of Alzheimer's disease (AD) and vascular disease in both male and female mice." (PMID 26316992, 2013). "For instance, a recent study has identified the mechanism by which an isoform of apolipoprotein E (ApoE) contributes to neurodegeneration in Alzheimer’s disease and demonstrated that vascular defects precede the neurodegenerative disease phenotype." (PMID 23305164, 2013). "Upregulation of genes included those involved with apoptosis (Ntn1, Adora1, and Ache) and Alzheimer’s disease (ApoE, Apbb1)." (PMID 24019935, 2013). "Apolipoprotein E (apoE) isoforms are known risk factors for cardiovascular disease (CVD) and Alzheimer disease (AD), likely due to their involvement in inflammation, elevated lipid levels, and oxidative stress." (PMID 23925498, 2013). "Further, APOE can interact with β-amyloid and tau proteins that are central to the pathogenesis of Alzheimer's dementia." (PMID 22577592, 2012). "ABCA1 had previously been shown to regulate both the amount of apoE in the brain, along with the extent of Aβ deposition, and represents a potential molecular target for lowering brain amyloid levels in Alzheimer's disease patients." (PMID 22512932, 2012). "The only replicated locus is APOE, which is a mortality locus that has previously been reported to be the major locus responsible for Alzheimer's disease, a well-known age-related disease." (PMID 21418511, 2011). "Since then, apoE has been widely studied in lipid metabolism, cardiovascular diseases, and neurodegenerative disorders such as Alzheimer's disease (AD) and Parkinson disease (PD)." (PMID 21772670, 2011). "Studies have shown the APOE gene to be associated with increased risk for coronary heart disease (CHD) and Alzheimer's Disease." (PMID 21276236, 2011). "Further longitudinal studies with measures of HDL subtypes, apolipoprotein A-1, apoE, and multiple dimensions of cognition and Alzheimer's disease biomarkers would be helpful." (PMID 21276232, 2011). "In previous studies, the ApoE protein has been proposed as a biomarker for prion diseases in addition to its role in the Alzheimer's disease pathway." (PMID 21629698, 2011). "Odds ratios for the association between Alzheimer's disease and PRNP codon 129 in different strata defined by APOE ε4 allele status (V129V genotype and V129 allele are taken as reference or non-exposed)." (PMID 21799773, 2011). "Unraveling the molecular details of the interaction between apolipoprotein E and the amyloid β peptide will yield insights into the relationship between Alzheimer's disease and lipid transport and metabolism." (PMID 20140182, 2010). "For both the rs3849942-rs10122902 haplotype in ALS and the APOE haplotype in Alzheimer's disease, only three of the four possible haplotypes are present, and the fourth does not exist in the population." (PMID 20801717, 2010). "ApoE has been widely studied in cholesterol transport, atherosclerosis and cardiovascular diseases, neurodegenerative diseases such as Alzheimer's disease, and mild cognitive impairment." (PMID 20613949, 2010).